IL33 (interleukin 33)
Diseases named in the same sentence as IL33 in open-access papers (continued):
Sharing a sentence is not in itself a finding about the gene and the disease.
Obesity (continued). "Elevated expression of IL-33 and its receptor ST2 has been reported in individuals with severe obesity, where increased levels were also associated with markers of inflammation." (PMID 39171751, 2024). "The goal of this systematic review and meta-analysis is to examine the role of IL-33 in obesity and T2D, assessing its potential in predicting disease progression." (PMID 39171751, 2024). "According to the random-effects model, the overall effect size was −79.95 (95% CI [−241.38; 81.48], P = 0.33), suggesting insufficient evidence to support a significant impact of obesity-related T2D on IL-33 levels." (PMID 39171751, 2024). "Research indicates that IL-33 plays a critical role in obesity and shows promising findings related to IL-33 and various cancers." (PMID 40236667, 2024). "Obesity was found to lower IL-33 expression and secretion in VAT DCs, which was primarily responsible for the attenuated Treg generation." (PMID 38566998, 2024). "Recent human studies have further highlighted the potential significance of IL-33 in the context of obesity and T2D." (PMID 39171751, 2024). "Conversely, in individuals with obesity, an increased expression of IL-33 within the cell lining of adipose tissue has been observed." (PMID 39171751, 2024). "Five studies involving 622 patients reported IL-33 serum levels in patients with T2D with obesity and healthy controls." (PMID 39171751, 2024). "This imbalance highlights the need to understand the discrepancies in regulating IL-33 at both tissue-specific and systemic levels amid obesity." (PMID 40236667, 2024). "Intriguingly, our findings reveal that obesity, particularly with a high saturated fat content, downregulates IL-33 expression and secretion in VAT DCs, thereby mediating decreased Treg differentiation." (PMID 38566998, 2024). "According to these results, we demonstrated that IL-33/ST2 signaling is deregulated in obesity and, importantly, altered ST2L/sST2 balancing drove the pro-fibrotic switch in gene expression." (PMID 36768322, 2023). "Another avenue of IL-33 influence is obesity-mediated inflammation in breast carcinoma, inducing the overexpression of IL-33 signaling molecules, which subsequently promote regulatory T cell infiltration, enhancing breast carcinoma aggressiveness." (PMID 37762328, 2023). "Here we further investigated the IL-33/ST2 effects on cardiac remodeling in obesity, focusing on molecular pathways linking adipose-derived IL-33 to the development of fibrosis or hypertrophy." (PMID 36768322, 2023). "In vivo data in the setting of obesity clearly show that GLP-1RA signaling inhibits allergen-induced IL-33 release in the airway." (PMID 35277168, 2022). "On the other hand, sST2, the soluble isoform of the IL-33 receptor ST2, secreted by adipocytes, attenuates the signaling of IL-33 and disrupts the ILC2 homeostasis in adipose tissue, thereby exacerbating obesity-associated insulin resistance." (PMID 35574038, 2022). "In response to high-fat diet (HFD) challenge, mice deficient in IL-33 or ST2 showed increases in obese phenotype and insulin resistance, suggesting the essential role of IL-33/ST2 signaling in reducing obesity and related complications." (PMID 35383145, 2022). "Concerning obesity, IL-33 is able to down-regulate excessive inflammation in adipose tissue by targeting immune cells expressing the ST2 receptor." (PMID 35807067, 2022). "This is consistent with Gata3-expressing ILC2s, which are reduced with obesity and produce IL33 – a type 2 cytokine that promotes glucose tolerance in mice and is the primary ligand for ST249." (PMID 35618862, 2022). "Contrarily, treatment with IL-33 reduces murine atherosclerosis development, and IL-33 polarizes macrophages (M2 phenotype), conferring protection against obesity and inflammation while improving glucose regulation." (PMID 33884963, 2021).
Obesity (continued). "Univariate and multivariate logistic regression analysis were performed on the association between each study group to explore the relationship between IL-33 and obesity metabolic phenotypes." (PMID 33541367, 2021). "Levels of this “satiety hormone” directly correlate with increased NE and IL-33 concentration in obese mice and men and leptin itself is increased in obesity and inflammation." (PMID 33673387, 2021). "Therefore, understanding whether inflammation and metabolic syndrome risk factors contribute to IL-33 production during obesity progression will provide important evidence for further clarification of the interrelationship between obesity, metabolic health and inflammation." (PMID 33541367, 2021). "IL-33 expression was shown to be up-regulated by obesity in white adipose tissue, but resident ILC2s were paradoxically decreased in mice and humans." (PMID 33541367, 2021). "Several reports have shown that IL-33 is important for maintaining immune cell homeostasis in adipose tissue as well as the involvement of adipose tissue microenvironment in the obesity-related inflammation and complications." (PMID 33541367, 2021). "In mouse obesity models, IL-33 plays a protective role by reducing obesity and increasing glucose and insulin tolerance." (PMID 33608010, 2021). "Further research on the mechanism of IL-33 in the occurrence and progression of obesity in different genders are also worth exploring." (PMID 33541367, 2021). "HMGB-1, S100, IL-33 are only some examples of how these danger signals are important in the etiopathogenesis of pathologies like heart failure, obesity, diabetes, hypertension." (PMID 34042528, 2021). "Similar to the results obtained during the development of obesity, the reduced expression of Il33 and Penk in the epiWAT of Gipr-/- BM mice was restored to WT BM control levels in Gipr-/-S100a9-/-BM mice." (PMID 33717200, 2021). "ST2L, sST2, and IL-33 are expressed in many tissues, including adipose tissue, and they are increased in obesity." (PMID 33608010, 2021). "Both ST2L and soluble ST2 (sST2) as well as IL-33 are expressed in many tissues including adipose tissue and are increased in obesity." (PMID 32101157, 2020). "Instead, our data suggest a role for the microbiome in diet/obesity-related differences in the impact of IL-33 on pulmonary responses to O3." (PMID 32326950, 2020). "Our data also support a role for the gut microbiome in obesity/diet-related differences in the impact of IL-33 on pulmonary responses to O3." (PMID 32326950, 2020). "Further research is now needed to clarify the role of PGE2 metabolism in the induction of ST2/IL-33 so as to pave the way to potential therapeutic strategies to prevent cardiac/fat tissue maladaptation driven by obesity." (PMID 31947646, 2020). "In murine models in the setting of obesity, IL-33 exerts protective effects by reducing adiposity and improving glucose and insulin tolerance." (PMID 32101157, 2020). "IL-33 has been shown to be metabolically protective in murine models of obesity in which various mechanisms have been described." (PMID 31073344, 2019). "It has been demonstrated that the IL-33/ST2 axis plays a protective role against obesity and/or insulin resistance and T2D in animal models." (PMID 31073344, 2019). "In direct contrast, IL-18 and IL-33 have been demonstrated to play a protective role in animal models of obesity-driven metabolic syndrome, although the precise mechanisms through which this occurs have not been identified." (PMID 31488830, 2019). "The IL-33/ST2 pathway plays a protective role against obesity, insulin resistance, and T2D in animal models." (PMID 31073344, 2019). "Previous studies suggested that IL‐33 exerts anti‐inflammatory properties in models of heart disease, obesity, and uveitis." (PMID 30478965, 2019). "The IL-33/ST2 axis is protective against obesity, insulin resistance, and type 2 diabetes (T2D) in animal models." (PMID 31073344, 2019).
Obesity (continued). "There is a variety of studies that IL-33 originally known as a Th2-dominant cytokine performs a beneficial role in the treatment of situations such as transplantation, obesity, and cardiovascular diseases." (PMID 30999922, 2019). "The VLDLR, IL33 and PTPRD genes were identified as the most interesting genes for obesity-susceptibility within 9p24." (PMID 29441128, 2018). "Ozone increases IL-33 in the lungs, and obesity augments the pulmonary effects of acute ozone exposure." (PMID 27472835, 2017). "In contrast, serum IL-33 was unchanged by obesity (7.1 ± 0.8 versus 6.0 ± 0.7 pg/mL in O3-exposed db/db versus WT mice, respectively) and was approximately 50% lower after O3 than air in both WT and db/db mice (data not shown)." (PMID 27472835, 2017). "A similar reduction is observed after anti-IL-13 in obese mice, suggesting that IL-33-dependent increases in IL-13 contributed to obesity-related increases in effects of O3 on baseline pulmonary mechanics (PBS values)." (PMID 27472835, 2017). "Data presented herein demonstrate a potential RNase-mediated mechanism for modulation of type 2 immunity by an IL-33–dependent ILC2-mediated mechanism to alter obesity and stabilize glucose homeostasis." (PMID 26490658, 2016). "This capacity of ω1 to induce IL-33 release and modulate obesity is dependent upon the molecule’s RNase activity." (PMID 26490658, 2016). "The mechanisms described in this study identify a central role for IL-33 in obesity and metabolic homeostasis." (PMID 26490658, 2016). "Endogenous opioid-like peptides, including the methionine-enkephalin produced by IL-33-activated ILC2, show promise as a potent therapeutic agent for obesity and obesity-associated diseases." (PMID 26549942, 2015). "IL-33 has been shown to be proinflammatory in certain conditions such as allergy and autoimmunity and to be protective in others such as obesity, atherosclerosis and cardiac fibrosis." (PMID 24886535, 2014). "In this line, we investigated the role of the IL-33/ST2 pathway as a mediator of obesity-induced ECM remodeling." (PMID 24265755, 2013). "On the other hand, IL-33 has protective effects in cardiovascular diseases, diabetes mellitus type 2 and obesity." (PMID 22349136, 2012). "We have previously shown that IL-33 exerts protective effects on glucose metabolism and obesity in obese diabetic (ob/ob) mice." (PMID 23112853, 2012). "In obesity, soluble ST2 receptors have been found that inhibit IL33 function, which, together with hypoxia-induced down-regulation of IL33 in lymphatics, might explain increased susceptibility for infection and inflammation in lymphoedema." (PMID 41439975, 2025). "Furthermore, immune responses in obesity are exacerbated by abnormal cytokine secretion from adipose tissue stromal cells (e.g., interleukin 33 (IL-33)), which impairs the development and functional capacity of Tregs and B cells in an inflammatory environment." (PMID 40564149, 2025). "Additionally, IL-33’s anti-inflammatory characteristics provide another possible intervention avenue, as chronic inflammation is a critical factor in obesity and a significant contributor to cancer development." (PMID 40236667, 2024). "Moreover, this study discovered that obesity diminished the expression and secretion of IL-33 derived from ATDCs, which is essential for driving Treg differentiation." (PMID 38566998, 2024). "IL-33 is essential for maintaining adipose tissue homeostasis and may help protect against obesity and type 2 diabetes." (PMID 40236667, 2024). "The mechanisms may involve IL-33’s regulation of specific immune cells related to obesity that contribute to disease aggressiveness." (PMID 40236667, 2024). "Research into the various roles of IL-33 in immune modulation, obesity, and cancer is essential." (PMID 40236667, 2024). "Some studies found that IL-33 improved obesity and metabolism." (PMID 38632591, 2024).
Obesity (continued). "The results presented in this systematic review and meta-analysis contribute to refining the knowledge about the relevance of IL-33 in individuals with obesity and T2D, guiding future research and enriching the broader discourse on therapeutic targets for metabolic disorders." (PMID 39171751, 2024). "Gaining insight into the complex connections between IL-33, obesity, and cancer could be crucial for the future management of these conditions, offering hope in the fight against these diseases." (PMID 40236667, 2024). "Thus, our data further emphasizes IL-33 derived from VAT DCs as the critical mechanism for modulating Treg populations in obesity." (PMID 38566998, 2024). "Additionally, our findings suggest that obesity conditions, particularly a high concentration of saturated fat, lead to reduced IL-33 mRNA expression and cytokine release in DCs." (PMID 38566998, 2024). "Its interaction with IL-33 can also enhance airway inflammation and induce obesity and asthma." (PMID 38365763, 2024). "Furthermore, IL-33 protects against adipose tissue inflammation during obesity by inducing Th2 cytokines in WAT and promoting the polarization of WAT macrophages toward an M2, an alternatively activated phenotype." (PMID 40236667, 2024). "Next, in an effort to comprehend the function of IL-33 in the emergence of obesity, we examined whether preadipocytes secreted IL-33 and whether its expression altered during adipogenesis." (PMID 38632591, 2024). "Targeting IL-33 signaling pathways and their downstream effects could help regulate obesity while exhibiting antitumor properties." (PMID 40236667, 2024). "Recent studies have shown that IL-33 and its receptor complex are expressed in adipose (fat) tissue, suggesting they may play a role in obesity." (PMID 40236667, 2024). "However, studies explicitly examining the direct effects of IL-33 in obesity-related cancer are limited." (PMID 40236667, 2024). "In children with overweight/obesity, the levels of pro-inflammatory cytokines, particularly IL-5, IL-17A, IL-33, TNF-α, and leptin, were also elevated, which is consistent with previous findings, indicating chronic low-grade inflammation associated with obesity." (PMID 39902293, 2024). "To explore whether obesity can alter IL-33 expression in DCs, we incubated BMDCs with AT-conditioned media (ATCM) from lean and obese VAT." (PMID 38566998, 2024). "Therapies based on IL-33 could reduce obesity-induced inflammation in fat tissue and other affected organs, subsequently lowering cancer risk." (PMID 40236667, 2024). "Statistical analysis of serum IL-33 levels in individuals with obesity and T2D." (PMID 39171751, 2024). "Many results have shown that IL-33 may have an unknown role in diabetes and cardiac complications of obesity because the precise effect of IL-33 in the progress of many metabolic diseases, including diabetes, seems to be unpredictable." (PMID 37238986, 2023). "During obesity, the level of circulating IL33 was upregulated." (PMID 37138165, 2023). "Circulating levels of IL-33 and sST2 in obesity are controversial." (PMID 36768322, 2023). "Targeting IL-33/ILC2s provides a novel approach to treat obesity and related metabolic diseases." (PMID 37138165, 2023). "Here we analyzed the mechanisms by which obesity alters IL-33/ST2 regulation and how this unbalance could affect myocardium gene expression." (PMID 36768322, 2023). "Administration of recombinant IL-33 could significantly ameliorate diet-induced obesity and related insulin resistance." (PMID 37138165, 2023). "In agreement, IL-33 null mice display glucose intolerance upon obesity." (PMID 36967785, 2023). "In addition, the combinatorial effect of IL-33 with leptin, an obesity-related adipokine, promotes eosinophilic airway inflammation in obesity-related SA." (PMID 35387021, 2021).
Obesity (continued). "Moreover, eosinophils, along with their IL-33-sensitive lymphoid counterparts ILC2s, are maintained in adipose tissue by sympathetic nerve signals and suppressed by the dearth of IL-33 that comes with obesity." (PMID 34613819, 2021). "Recent studies suggest that IL-33/ST2 gets a new direction in the treatment of obesity with IR." (PMID 33472506, 2021). "Indeed, IL33 is a strong modulator of adipose tissue homeostasis in both physiological and pathological settings, such as obesity." (PMID 34207683, 2021). "In addition, IL-33 promotes the beiging of white adipocytes and energy expenditure by activating group 2 innate lymphoid cells (ILC2s) in adipose tissue, contracting obesity and its related disorders." (PMID 33541367, 2021). "It is possible that in some cases of obesity-induced inflammation there may be cadherin-11 overexpression leading to less IL-33 in adipose tissues." (PMID 34489979, 2021). "Therefore, significantly increased serum levels of IL33 were found in the adipose tissue of patients with severe obesity." (PMID 34207683, 2021). "In the present study, our results showed that circulating levels of IL-33 in overweight/obese subjects were significantly higher than those in HC subjects, which was partly in agreement with the findings of IL-33 expression in human adipose tissue was upregulated by severe obesity." (PMID 33541367, 2021). "It has recently been reported that circulating levels of IL-33 are elevated by obesity." (PMID 34074279, 2021). "What’s more, the contradiction between our results and those of previous studies indicates that IL-33 might have a more complex relationship with the progression of obesity." (PMID 33541367, 2021). "Caloric restriction for 3 and 6 months significantly attenuated the increased expression levels of ELOVL4 in the obesity group, while a significant reduction of IL-33 expression levels was observed in the obese patients with a 6-month period of caloric restriction treatment." (PMID 32581837, 2020). "The observation that IL-33 increases the expression of the leptin receptor in some cell types also suggest that there might be differences in the role of IL-33 in db/db mice versus mice with other forms of obesity." (PMID 32326950, 2020). "Thus, IL-33-driven WAT biogenesis suggests another role for an ILC2-inducing cytokine in regulating obesity." (PMID 32581740, 2020). "The data are consistent with the hypothesis that IL-33 protects against the development of innate AHR in mice with diet-induced obesity." (PMID 32326950, 2020). "Consistent with IL33 being considered as ‘alarmin’, its expression was higher in the Wg of M-HFD mice than in that of M-Chow mice, suggesting inflammation and tissue damage associated with obesity." (PMID 32240221, 2020). "However, it is unlikely that these obesity-related differences in the impact of IL-33 on systemic type 2 cytokines account for obesity-related differences in the impact of IL-33 on O3-induced AHR." (PMID 32326950, 2020). "However, ST2 deficiency did cause significant reductions in serum IL-1β, TNFα, and CCL5 in the HFD-fed mice, suggesting that IL-33 contributes to aspects of the systemic inflammation of obesity." (PMID 32326950, 2020). "In view of the role PTGES-2 in obesity and in the control of intracellular cAMP concentrations through PGE2 receptors, we investigate the possible association between PTGES-2 and EPAC2 cAMP effector and ST2/IL-33 mechanosensitive genes." (PMID 31947646, 2020). "We have reported that IL-33 contributes to these effects of obesity in db/db mice." (PMID 32326950, 2020). "The purpose of this study was to determine whether IL-33 also contributes to obesity-related changes in the response to ozone in mice with diet-induced obesity." (PMID 32326950, 2020).